NF2 (NF2, moesin-ezrin-radixin like (MERLIN) tumor suppressor)
Diseases named in the same sentence as NF2 in open-access papers (continued):
Sharing a sentence is not in itself a finding about the gene and the disease.
meningioma (continued). "It was observed that higher levels of these analytes characterized meningiomas with NF2 mutations." (PMID 40004036, 2025). "The most predominant variant persistently present in convexity meningiomas is the NF2 mutation." (PMID 40867323, 2025). "Also, compared to other genotypic variants, NF2-mutated meningiomas have larger tumor sizes and higher proliferation indexes." (PMID 40447281, 2025). "Combined Dasatinib and dual mTORC1/2 inhibition led to stronger growth suppression, suggesting co-targeting Eph RTK/SFK and mTORC1/2 pathways may benefit NF2-deficient meningiomas." (PMID 41200151, 2025). "Cas9 functions were activated by Cre in these cells and caused mutations of the four genes (Nf2, P15Ink4b, P16Ink4a, and P19Arf) in meningeal cells, which could lead to tumorigenesis of meningioma in the skull base of Cas9 mice." (PMID 39996452, 2025). "Another study of 88 cases of sporadic meningiomas found that 49% of cases had 22q loss, 24% had somatic NF2 mutations and 26% had aberrant NF2 promoter methylation, and that epigenetic NF2 inactivation was the sole cause of NF2 deficiency in 17% of meningiomas." (PMID 40815185, 2025). "Furthermore, this data identified Annexin-3 overexpressed in meningiomas with NF2 mutations, which has been previously reported to be upregulated in other cancers and is known to enhance cellular proliferation through the Notch and MAPK/ERK/JNK pathways." (PMID 40562609, 2025). "Notably, the SMARCB1 gene is located on chromosome 22q11, like the neurofibromatosis 2 (NF2) gene, which is associated with meningiomas, also a female-predominant pathology." (PMID 40052132, 2025). "Although ANXA3 is highly expressed in grade 1 and 2 meningioma tissues as observed by Western blot analysis, the NF2 phenotype, characterised by loss of function due to mutations, truncations, and/or deletions, is frequently observed in higher-grade meningiomas or more advanced molecular groups." (PMID 40562609, 2025). "Therefore, this study aimed to profile acylcarnitines with short, medium, and long acyl chain lengths in meningiomas to assess their changes in tumors with different NF2 mutation statuses." (PMID 40004036, 2025). "Methylation analysis and investigation of other gene alterations associated with non‐NF2 meningiomas may be helpful to determine the NF2 status of these cases." (PMID 40815185, 2025). "Notably, patients with multiple tumors predominantly presented with a combination of schwannomas and meningiomas, which supports the second diagnostic criterion for NF2-SWN." (PMID 41209567, 2025). "The presence of chromosome 22q loss may be a marker for meningiomas with loss of NF2/Merlin expression." (PMID 40603285, 2025). "Meningiomas are frequently linked to neurofibromatosis (NF2)-related schwannomatosis, and somatic NF2 mutations may contribute to sporadic cases." (PMID 41246661, 2025). "Biallelic mutations in the NF2 gene are the most frequent cause of meningiomas across all grades." (PMID 40562609, 2025). "The NF2 gene encodes a tumor suppressor protein called Merlin, whose inactivation has been implicated in several cancers, such as neurofibromatosis, mesothelioma, breast cancer, and meningioma." (PMID 39712860, 2025). "For people with only meningiomas, germline testing may also include SMARCE1 and SUFU, which are rare causes of predisposition to non-NF2-related meningiomas." (PMID 41284083, 2025). "Importantly, our patient did not meet clinical or radiological criteria for neurofibromatosis type 2 (NF2), a known cause of multiple meningiomas." (PMID 41287662, 2025). "One could have expected less merlin immunoreactivity in convexity meningiomas, as NF2-mutated meningiomas are more frequent in this location." (PMID 40447281, 2025). "The underlying tumor genomics, for example, neurofibromatosis Type 2 (NF2)–gene mutation associated with more aggressive behavior of atypical and higher grade meningioma, might also correlate with an increased predisposition to seizures." (PMID 40677941, 2025).
meningioma (continued). "Despite no history of prolonged exogenous progesterone exposure, genetic testing revealed a deletion of the NF2, indicating it may be a high-risk factor for this meningioma." (PMID 40502635, 2025). "Also, NF2-deficient meningiomas provide a complementary example of how tumor genetics rewires Eph-linked networks and mandates combination approaches." (PMID 41200151, 2025). "The relevance of the specific target found in the most common driver mutation in meningiomas (NF2) was validated in vitro using both lower and higher-grade meningioma and further, the higher-grade meningioma was analysed in vivo using an NOD scid gamma (NSG) mouse model." (PMID 40562609, 2025). "However, 33 of the 48 meningiomas with NF-2 copy number loss were high-grade tumors, while only 19 of the 44 meningiomas with NF-2 wild type were high-grade tumors (p = 0.01)." (PMID 38611661, 2024). "NF2-related schwannomatosis is a tumor predisposition syndrome caused by loss-of-function alterations in NF2 resulting in the development of schwannomas, meningiomas, and ependymomas." (PMID 38265489, 2024). "Next, we detected the expression of PD‐L1 in NF2‐associated meningiomas and found that positive expression of PD‐L1 was observed in 38.46% (5/13) of NF2‐associated meningiomas according to IHC and 53.85% (7/13) of NF2‐associated meningiomas according to Western blotting." (PMID 38828669, 2024). "The neurofibromatosis-2 (NF2) gene was the first gene to be implicated in meningioma development." (PMID 38695575, 2024). "Furthermore, we identified SNV/INDELs unique to each focus, with NF2 mutation prevalent in the transitional meningioma and CREBBP mutation in the chordoid meningioma." (PMID 39066986, 2024). "In meningiomas, tumors with NF-2 mutations tend to develop calcifications, whereas those with S100 protein expression may not show neovascularization or calcification." (PMID 38611661, 2024). "NF2 inactivation is associated with atypia and enriched in higher-grade meningiomas." (PMID 38730704, 2024). "Results also revealed that EGF (100 ng/mL, 48 h), an agonist of EGFR signaling, could remarkably upregulate PD‐L1 protein expression in NF2‐associated meningioma cells, demonstrating that EGF can induce an increase in PDL1 expression." (PMID 38828669, 2024). "Targeting PD‐L1 could be helpful for restoring the function of tumor‐infiltrating lymphocytes and inducing apoptosis to inhibit tumor proliferation in NF2‐associated meningiomas." (PMID 38828669, 2024). "Thus, to improve patient prognosis, there is an urgent need to study the biological features of NF2‐associated meningiomas and find a new effective treatment method." (PMID 38828669, 2024). "However, some unique groups of meningioma patients including those with NF2-associated schwannomatosis, RIMs, and pediatric patients have been largely excluded from most contemporary molecular studies." (PMID 38695575, 2024). "Further results confirmed that downregulation of PD‐L1 could inhibit tumor cell proliferation, promote apoptosis, and suppress the inhibitory effect of tumor cells on T‐cell activation and cytotoxicity in NF2‐associated meningiomas." (PMID 38828669, 2024). "The most common genetic aberration in meningiomas is functional loss of NF2 and occurs in both low- and high-grade meningiomas, whereas NF2-wildtype meningiomas are enriched for recurrent mutations in TRAF7, KLF4, AKT1, PI3KCA, and SMO and are more frequently benign." (PMID 38571886, 2024). "Furthermore, we designed a PD‐L1‐silencing construct and silenced PD‐L1 in NF2‐associated meningioma cells." (PMID 38828669, 2024). "Notably, this finding was consistent with prior research indicating that individuals with NF-2 mutations tend to develop meningiomas characterized by higher grades, worse prognoses, and increased recurrence rates compared to those without these mutations." (PMID 38611661, 2024).
meningioma (continued). "Moreover, EPHA2 and EPHB1 are overexpressed in neurofibromatosis type 2 gene (NF2) deficient meningiomas, and their pharmaceutical targeting with Dasatinib favors patients’ prognosis." (PMID 38612645, 2024). "Furthermore, we validated the roles of PD‐L1 downregulation in NF2‐associated meningioma progression in vivo." (PMID 38828669, 2024). "This implies that NF-2 copy number loss may serve as an indicator of more aggressive meningiomas, consistent with previous research." (PMID 38611661, 2024). "NF-2 is an inherited condition that increases the risk of developing specific nervous system tumors such as bilateral vestibular Schwannomas, multiple spinal and peripheral Schwannomas, meningiomas and ependymomas." (PMID 39415595, 2024). "In this study, we show that positive expression of PD‐L1 was observed in 38.46% (5/13), and CD3‐ and CD8‐positive T lymphocytes were present in 100% (13/13) of NF2‐associated meningiomas, indicating the possibility of anti‐PD‐L1 therapy for NF2‐associated meningiomas." (PMID 38828669, 2024). "The percentages of CD4+CD69+ and CD8+CD69+ cells were analyzed, and the results showed that when T cells were cocultured with siPD‐L1‐transfected NF2‐associated meningioma cells, the expression of CD69 on both CD4+ and CD8+ T cells was partly reduced compared with that in the siPD‐L1‐NC group." (PMID 38828669, 2024). "Several studies conducted on patients with NF-2, including those suffering from skin cancers, vestibular schwannomas, and meningiomas, have posited that the loss of heterozygosity, including allelic loss of NF-2, may contribute to neoplastic developments." (PMID 38611661, 2024). "Our analysis also suggests that the presence of BRCA2 may represent a secondary or potentially modifying genetic event; however, this interpretation warrants cautious consideration, particularly given the established role of NF2 mutations in meningioma." (PMID 39935847, 2024). "In addition, functional inactivation of PTEN (a negative regulator of the PI3K pathway; frequently achieved by loss of chromosome 10) is also enriched in higher-grade meningiomas (most frequently NF2 mutant)." (PMID 38571886, 2024). "More precisely, high levels of EPHA2 and EPHB4 expression could distinguish high-grade gliomas and NF2-deficient meningiomas." (PMID 38612645, 2024). "This correlation between NF-2 mutations and psammoma bodies underscores the potential diagnostic and prognostic significance of such histological attributes in distinguishing between meningiomas based on their imaging features on SWI." (PMID 38611661, 2024). "PD‐L1 is heterogeneously expressed in NF2‐associated meningiomas." (PMID 38828669, 2024). "Taken together, these findings may lead to the development of immunotherapy for NF2-associated meningiomas." (PMID 38879686, 2024). "Additionally, partial responses to defactinib monotherapy were reported in meningioma patients with NF2 mutations as part of the NCI-MATCH trial (NCT04439331)." (PMID 39034922, 2024). "We are curious about how NF2‐associated meningiomas respond to PD‐L1‐targeting therapy." (PMID 38828669, 2024). "The purpose of these studies was to find cost-effective surrogate markers, like NF-2 mutations and S100 protein expression, that could help predict how meningiomas would behave." (PMID 38611661, 2024). "PD‐L1 expression was also examined in NF2‐associated meningioma tissues." (PMID 38828669, 2024). "In addition, up to 50% of patients with germline NF2 mutations will develop one or multiple meningiomas during their lifetime, in addition to other tumors (most commonly Schwannomas)." (PMID 38571886, 2024). "Here, we test the hypothesis that understanding signaling mechanisms associated with NF2/Merlin itself may shed light on meningioma biology and elucidate strategies to define meningioma biology pre-operatively using non-invasive imaging techniques." (PMID 39251601, 2024). "Neurofibromatosis type 2 (NF2) mutation is also associated with meningiomas." (PMID 38368566, 2024).
meningioma (continued). "As the PI3K–AKT–mTOR pathway plays a key role in NF2,41, 42, 43 we hypothesized that this pathway may be responsible for controlling PD‐L1 expression in NF2‐associated meningiomas." (PMID 38828669, 2024). "We next analyzed whether the spectrum of NF2 mutations in SP-EPN differed from NF2 mutations found in schwannoma and meningioma." (PMID 38265489, 2024). "Additionally, NF-2-associated meningiomas often exhibit intratumoral calcification, which is also related to a poor prognosis." (PMID 38611661, 2024). "However, in vivo studies revealed that the combined depletion of both molecules promoted meningioma tumorigenesis compared with the single loss of Nf2 in Nf2-floxed mice." (PMID 38879686, 2024). "Furthermore, the effect of PD‐L1 downregulation in NF2‐associated meningioma cells on the influence of exT cell cytolytic activity was also evaluated." (PMID 38828669, 2024). "Studies have shown that NF2 variants, including shift mutations, allelic inactivation, and missense mutations, could be detected in approximately 60% of meningiomas." (PMID 36969005, 2023). "Furthermore, loss of the NF2 suppressor gene at chromosome 22 has been demonstrated in a higher percentage (50–60%) of meningiomas, and supratentorial meningiomas with NF2 alterations had higher MIB-1 indices and a shorter time to tumor progression." (PMID 37370707, 2023). "Indeed, alterations in NF2 have been recognized as meningioma’s driver mutation, being present in about 50% of sporadic meningiomas." (PMID 38137885, 2023). "Group 1 meningiomas have the best prognosis, are free of NF2 mutations and chromosomal instability, may include AKT1, TRAF7, or KLF4 mutations, and are predicted good responses to cytotoxic therapies." (PMID 38001599, 2023). "Taken together, these results indicate that no solid conclusions about the repressive DREAM complex function in NF2-2 meningiomas with the loss of chr22q and chr1p could be drawn, potentially due to a lack of power." (PMID 36937440, 2023). "Moreover, in meningioma-related epilepsy, NF2 mutation was shown to be predictive marker for seizures, via an indirect mediation effect with atypical histology and edema." (PMID 37511737, 2023). "We then used uncultured tumor resection tissue from an NF2 mutation-driven grade II meningioma (MG-II) to investigate whether tumors engrafted onto OBSCs maintained the genetic profile of the parent tumor." (PMID 37192626, 2023). "Merlin inactivation, due to mutations in NF2, is involved in about half of sporadic meningiomas." (PMID 38001599, 2023). "Moreover, understanding the genomic and molecular pathogenesis of NF2 variants will provide insights into better knowledge about tumorigenesis-related manifestations, such as meningioma, spinal schwannomas, ependymomas, and dermal schwannomas." (PMID 37217995, 2023). "Likewise, KLF4 mutations seem to occur only in NF2-intact meningiomas and frequently co-exist with alterations of TRAF7." (PMID 36181606, 2023). "Previous work by our lab and others identified robust associations of meningioma genomic drivers and tumor locations, whereby samples with bi-allelic loss of NF2 tend to occur in the cerebral convexities and spine, while other meningiomas are enriched in the skull base." (PMID 37805627, 2023). "Notably, MO models were successfully established from both NF2‐mutated and NF2‐wildtype tumor samples, indicating that this protocol is adaptable to meningiomas with different genetic landscapes." (PMID 36994665, 2023). "SMARCB1 mutation has also been shown to co-occur in NF2-mutated meningiomas." (PMID 37760490, 2023). "In fact, 60–80% of meningiomas have a loss of one copy of 22q, which harbors the neurofibromatosis type 2 (NF2) gene, and this loss is usually coupled with alterations of the remaining NF2 allele." (PMID 38001599, 2023). "MenG B meningiomas were NF2-deficient with 22q loss, but had a low degree of chromosomal instability, and could not be distinguished from MenG A based on clinical outcome." (PMID 36840836, 2023).